LINC01512 (long independently transcribed non-coding RNA 1512)
Synonyms: LOC100132354; TCONS_00011120; HI-LNC77
Gene: Long non-coding RNA gene on chromosome 6 (43,890,891 to 43,938,218, forward strand). Ensembl gene ENSG00000289313.
Diseases named in the same sentence as LINC01512 in open-access papers:
LINC01512 is named in the same sentence as 2 diseases in open-access papers, as found by Europe PMC text mining. Sharing a sentence is not in itself a finding about the gene and the disease. The quoted sentences say what the papers report.
lung adenocarcinoma (1 paper, 2017). A carcinoma that arises from the lung and is characterized by the presence of malignant glandular epithelial cells. "LINC01512 is an oncogenic lncRNA gene that promotes the progression and distinctly enhances the oncogenic ability in lung adenocarcinoma." (PMID 28569418, 2017).
lymph node metastasis (1 paper, 2017). "qPCR revealed that LINC01512 overexpressed and closely related to lymph node metastasis and TNM stage in LAD patients." (PMID 28569418, 2017).